MMP9 (matrix metallopeptidase 9)
Diseases named in the same sentence as MMP9 in open-access papers (continued):
Sharing a sentence is not in itself a finding about the gene and the disease.
Stroke (continued). "Numerous studies have documented increases in matrix metalloproteinases (MMPs), specifically MMP-9 levels following stroke, with such perturbations associated with disruption of the blood brain barrier (BBB), increased risk of hemorrhagic complications, and worsened outcome." (PMID 26973468, 2016). "Even in embolic stroke treated with tissue plasminogen activator (tPA), where MMP-9 activation has been associated with increased hemorrhagic transformation (HT) and worsened outcomes in animals and humans, we have shown candesartan to be acutely vascular protective." (PMID 25147751, 2014). "This might be a consequence of the limited number of patients with cerebral ischemia (n = 7) since an increase of MMP-9 has been described in numerous animal and clinical stroke studies underlining the importance of MMP-9 in cerebral ischemia." (PMID 23555845, 2013). "MMP9 has been implicated in increasing neurological deficit, infarct volume and stroke severity." (PMID 24303036, 2013). "We also found a pharmacogenetic effect of the MMP9 R668Q polymorphism to increased stroke risk, although this association may be due to the small number of events (17 in the chlorthalidone group, 3 in the amlodipine group)." (PMID 21887284, 2011). "After adjusting for baseline characteristics, the association between the MMP9 R279Q variant and stroke was modestly significant, with participants carrying the minor G allele having decreased risk of stroke (HR = 1.00 for AA, 0.87 for GA, 0.91 for GG; P = 0.04, additive genetic model)." (PMID 21887284, 2011). "Therefore, detection of MMP-9 gene methylation in ischaemic stroke patients may serve as a novel approach to predict the risk of stroke." (PMID 35002488, 2021). "The TT and CT genotypes of the MMP-9 gene-1562 C/T polymorphism (SNP rs3918242) and its hypomethylation increase the individual’s susceptibility to stroke in the Indian population and the MMP-9 gene may be considered as a candidate gene for determining predisposition to ischaemic stroke." (PMID 35002488, 2021). "However, the pathophysiological mechanisms of these variants in MMP‐9 gene effect on initial stroke severity and END risk remain unclear." (PMID 31012282, 2019). "Moreover, upregulation of MMP-9 may be implicated in the pathological processes of brain disorders, including stroke, AD, multiple sclerosis, and malignant glioma." (PMID 30562971, 2018). "Moreover an increased level of MMP-9 is a predictive factor of increased mortality due to stroke and impaired healing of ulcerations associated with diabetic foot, and a MMP-9 to TIMP-1 ratio together with the level of MMP-10 is tightly correlated to severity and mortality of sepsis." (PMID 28104930, 2016). "Thus, it is an intriguing hypothesis that the concerted action of MMP-9 and TF may be a key mechanism of plaque destabilisation in cerebrovascular disease patients who are at high risk of stroke." (PMID 22493647, 2009). "MMP-9 levels increase in plasma within the initial 2–6 hours post-stroke, leading to BBB disruption." (PMID 40364646, 2026). "It was found that elevated MMP-9 levels were significantly associated with a composite endpoint of amaurosis fugax, TIA, stroke and central retinal artery occlusion in one of the studies included." (PMID 40364266, 2025).
Stroke (continued). "HMGB1 was significantly increased in plasma after tPA treatment in stroke patients, promoting the release of MMP9, and leading to blood–brain barrier disruption and hemorrhagic transformation." (PMID 38740617, 2025). "The serum MMP-9 level depends mainly on leukocyte and endothelial secretion, and augments significantly in many conditions (such as trauma or stroke)." (PMID 40076533, 2025). "This process occurs through the secretion of matrix metalloproteinases MMP-2 and MMP-9, ultimately leading to enhanced neurological recovery following a stroke." (PMID 41480312, 2025). "In studies utilizing MMP-9 knockout stroke models, researchers noted significantly higher levels of the tight junction protein ZO-1, which correlated with a substantial decrease in BBB permeability and a marked reduction in cerebral edema." (PMID 41480312, 2025). "CBD amino quinone derivatives have been found to reduce BBB leakage in stroke mice, potentially through inhibiting MMP-9 expression in brain tissue." (PMID 41551042, 2025). "MMP-9 contributes to a wide variety of brain disorders, including epilepsy, schizophrenia, autism spectrum disorders, brain damage, stroke, neurodegeneration, pain, and brain tumors." (PMID 40076533, 2025). "To evaluate the effect of MMP-9 on post-stroke neuronal excitability changes, we assessed the impact of the injury on the animals’ susceptibility to the subconvulsant injection." (PMID 38255970, 2024). "Our group and others have shown that the amount of matrix metalloproteinase (MMP)-9 in the blood, a biomarker relevant for the prognosis of stroke and cancer, can be critically affected by HMWH, an effect potentially impeding adequate treatment decisions." (PMID 39337591, 2024). "Intriguingly, treatment of mouse stroke models with a neutralising human IgG monoclonal antibody, L13 (anti-MMP9), significantly reduces brain tissue injury and improves neurological outcomes of mice when administered at the onset of reperfusion." (PMID 39707430, 2024). "This suggests that it is reasonable to expect a more severe secondary cascade in blood vessels with high MMP-9 expression following stroke and r-tPA treatment." (PMID 39273389, 2024). "We found that the expression of MMP-9 in the stroke hemisphere of r-tPA-treated mice was highly dependent on ischemic time and was significantly greater in r-tPA-treated mice than control mice with 2 h and 4 h ischemia." (PMID 39273389, 2024). "In the present study, we set out to investigate the role of matrix metalloproteinase-9 (MMP-9) in stroke-evoked epilepsy development." (PMID 38255970, 2024). "Of note, recently, either partially or just poorly selective MMP-9 inhibitors have been shown to offer therapeutic potential towards epileptogenesis, further supporting the need to assess a role of MMP-9 in post-stroke epileptogenesis." (PMID 38255970, 2024). "Serum levels of ox‐LDL, MMP‐9 and 8‐OHdG in stroke/non‐stroke patients with stable and unstable atherosclerotic plaque qualified to CEA." (PMID 39039803, 2024). "A biomarker panel examined among 89 patients with stroke and 38 HC consisting of BNP, D-dimer, MMP-9, and S100B, and a derived multimarker index, showed higher values in stroke patients compared to HC." (PMID 39091977, 2024). "Similar analysis of genes in the Disease and Function categories indicated that female MMP-3 KO stroke brains had decreased expression of leukocyte migration genes Ccr1, Pecam1, Mmp9, Ccl6, Icam2, and Ccl11." (PMID 39000490, 2024). "The findings show that MMP-9 is a key player in post-stroke epileptogenesis, presenting opportunities for future therapies and expanding our understanding of acquired epilepsy." (PMID 38255970, 2024). "A double-blind, randomized, vehicle-controlled study found that UA can improve the prognosis of stroke by reducing the level of MMP-9 and alleviating oxidative stress." (PMID 39119562, 2024).
Stroke (continued). "Herein, we have investigated the impact of MMP-9 on post-stroke neuronal excitability, particularly in the context of epileptogenesis." (PMID 38255970, 2024). "This novel herb-based product improves motor control evaluated using the NIHSS and stroke serum biomarkers, such as MMP-9, VCAM-1, and s100β, in patients who experienced transient ischemic stroke and minor ischemic stroke." (PMID 39599732, 2024). "Experimental stroke studies have revealed the crucial involvement of MMP-9 in blood-brain barrier permeability." (PMID 39679379, 2024). "It activates MMPs, such as MMP-9, which was shown to be elevated in venous blood from stroke patients that received tPA treatment." (PMID 39273389, 2024). "In contrast, no such correlation has been noted in studies examining the acute phase of stroke, during which MMP-9 is known to be primarily involved in processes such as blood–brain barrier damage and neuroinflammation." (PMID 38891934, 2024). "MMP-9 induces complete basal lamina and TJ breakdown, exacerbating barrier impairment and vasogenic edema post-stroke." (PMID 38872149, 2024). "Post-stroke patients exhibit significantly higher concentrations of MMP-9 compared to healthy volunteers, and it has been found to have predictive value for hemorrhagic transformation and for post-stroke cognitive impairment." (PMID 38891934, 2024). "Currently, there is no clear scientific evidence to explain the phenomenon of correlation between MMP-9 and depression improvement as regards stroke laterality." (PMID 38891934, 2024). "Studies have suggested a correlation between increased MMP-9 activity and larger stroke volumes, indicating a potential link between MMP-9 levels and the extent of vascular damage." (PMID 38255970, 2024). "We evaluated the potential value of 4 key hub genes (ADM, PTGS2, VCAN, and MMP9) in stroke diagnosis." (PMID 39519172, 2024). "Earlier studies have indicated that increased levels of MMP-9 correlate with poor neurological outcomes following stroke therapy 22,23." (PMID 38169640, 2024). "They demonstrated a significant increase in the levels of copeptin, NT-proBNP and MMP-9 for stroke patients compared to healthy controls." (PMID 39777314, 2024). "In recent years, clinical evidence has increasingly supported the adverse impact of MMP‐9 in stroke patients undergoing thrombolysis therapy." (PMID 38379112, 2024). "The results indicate that MMP-9 offers particular promise as a biomarker of post-stroke cognitive recovery: MMP-9 level in plasma decreased during three-week rehabilitation, with the changes correlating with improvements in cognitive function." (PMID 38891934, 2024). "The volcano plot indicates significant downregulation of genes already implicated in inflammation and apoptotic cell death following stroke such as Ccr5, Casp8, Icam2, Mmp9, Pecam1, and Il6." (PMID 39000490, 2024). "We examined the effect of ischemia and r-tPA treatment at different ischemic time points (1, 2, and 4 h) on the comparative expression levels of MMP-9, -3, and -2 in the brain post stroke." (PMID 39273389, 2024). "Nonetheless, to the authors’ knowledge, this represents the most comprehensive systematic review of blood-based protein biomarkers for stroke: MMP-9, TNF-alpha, VCAM-1, ICAM-1, E-Selectin, P-Selectin, L-Selectin, NSE, GFAP, S100, S100B, BNP, and NT-proBNP." (PMID 39091977, 2024). "The present study follows up on these findings by examining the correlation between MMP-9 and functional status in stroke patients." (PMID 38891934, 2024). "Following a stroke, neutrophils are the primary source of MMP-9 in both peripheral blood and brain tissue." (PMID 39606238, 2024). "A potentially significant diagnostic aspect involves exploring the correlation between serum MMP-9 levels and epileptic activity in stroke patients." (PMID 38255970, 2024). "It has been reported that the improvement in stroke severity is associated with neuroplasticity, which, in turn, relates to VCAM-1, MMP-9, S100β, and vWF." (PMID 39599732, 2024).
Stroke (continued). "A study of 188 AIS patients and 90 stroke mimics reported on a biomarker panel including IL-6, S100B, and MMP-9 which was incorporated in a clinical data assessment (age, AF, Face-Arm-Speech-Test results)." (PMID 39091977, 2024). "In blood, MMP-9 is mainly produced by monocytes, and its expression is a relevant biomarker, e.g., for the prognosis of stroke." (PMID 39337591, 2024). "The administration of anticoagulant therapy, including heparin, synthetic heparin, and direct thrombin inhibitors, has been observed to result in an elevation of MMP-9 levels in stroke patients." (PMID 39351476, 2024). "A previous study confirmed that OT treatment suppressed brain MMP-9 expression in a stroke mouse model, which is somewhat consistent with our findings." (PMID 39113801, 2024). "Although Tregs have been found to protect against neurovascular destruction after stroke by inhibiting peripheral neutrophil-derived MMP-9, these findings were based on a study conducted in young animals." (PMID 37728582, 2024). "Among the 23 MMPs that have been identified to date, MMP-2 and MMP-9 are the most widely studied in stroke due to their critical role involved in pathogenesis of BBB breakdown and subsequent vasogenic edema." (PMID 39273389, 2024). "We highlight the role of matrix metalloproteinase-9 (MMP-9) in post-stroke epileptogenesis, emphasizing MMP-9 involvement in mouse models and its potential as a therapeutic target." (PMID 38255970, 2024). "In a receiver operator curve (ROC) analysis to differentiate between AIS and stroke mimics based on MMP-9 levels, a cut-off value of 199 ng/mL showed a sensitivity of 65% and a specificity of 53%." (PMID 39091977, 2024). "In primate models of stroke, a transient increase in plasma MMP‐9 activity is detected within 2 hours after reperfusion." (PMID 38379112, 2024). "MMP-9 (Matrix metalloproteinase-9): This enzyme is involved in the breakdown of the blood-brain barrier and can be used to detect stroke and other brain injuries." (PMID 40777969, 2024). "The results of zymography showed that MMP-9 activity was markedly increased in lesions in patients 2–4 days after stroke compared to intact brain areas, whereas there was virtually no change in MMP-2 activity." (PMID 37511788, 2023). "In recent years, there are many studies on the relationship between BDNF and stroke, but little attention has been paid to proBDNF and MMP-9." (PMID 37735708, 2023). "Conversely, elevated MMP-9 serum concentrations compared to controls have been noted in the hyperacute period of stroke; however, MMP-9 also appears to play a role in damaging the blood-brain barrier and regulating inflammation." (PMID 37371326, 2023). "Intracranial injection of MSCs was reported to prevent BBB leakage via regulation of intercellular adhesion molecule-1 (ICAM-1) and MMP-9 in a mice model of stroke." (PMID 37605722, 2023). "Post-stroke recovery mechanisms remain poorly understood; however, circulating molecules related to neuroplasticity, such as MMP-9, VEGF and IGF-1, can influence the outcome when accompanied by extensive rehabilitation." (PMID 37371326, 2023). "The CC, CT, and TT genotypes of the MMP-9 gene were in Hardy–Weinberg equilibrium for patients with different stroke etiologies and for the total and control groups separately (p > 0.1 for each group) (Szczudlik and Borratyńska, 2010)." (PMID 37206663, 2023). "Our findings indicate that MMP-9 serum levels decreased by 24% (p = 0.032) in stroke patients after a three-week course of rehabilitation, both as raw data and following adjustment for sex and age." (PMID 37371326, 2023). "In a study of 168 stroke patients, MMP-9 at a concentration > 181.7 ng/mL showed a sensitivity of 82.9%, a specificity of 81.3%, a PPV of 48%, and an NPV of 95.8% in predicting haemorrhagic transformation." (PMID 37511304, 2023).
Stroke (continued). "In the patients whose autopsy material was analyzed several months or years after stroke, the activity of MMP-9 was increased to a much lesser extent in the foci, though, at the same time, increased activity of MMP-2 was observed." (PMID 37511788, 2023). "During a stroke, disruption of the endothelial layer results in the release of molecules such as MMP-9, E-selectin, P-selectin, VonWillebrand factor, and exposure of the extracellular matrix." (PMID 37511304, 2023). "Conversely, TNF-α production is triggered by ischemia during stroke as an inflammatory response, leading to the activation of MMP-9 expression related to secondary bleeding in the BBB." (PMID 37570794, 2023). "Human IgG monoclonal antibody (mAb) L13 has specificity for neutralizing MMP-9 and has therapeutic effects in mouse stroke models." (PMID 37483355, 2023). "As neuromodulators, BDNF, pro-BDNF, and MMP-9 are closely related to the recovery of neurological and psychiatric diseases such as stroke." (PMID 37735708, 2023). "MMP-13 has been shown to have a similar pattern to MMP-2 and MMP-9, i.e., it promotes HT in the acute phase of stroke and is involved in the regeneration of damaged tissue in the late phase." (PMID 37511788, 2023). "The matrix metalloproteinase 9 (MMP-9) protein of the Mmp9 gene was shown to be activated during inflammation and can be used as a prognostic indicator of stroke severity." (PMID 37510352, 2023). "In the acute phase of stroke in rodent models, the increased levels of MMP-9 protein were detected within 2–24h after cerebral artery occlusion." (PMID 36835040, 2023). "Our findings indicate that MMP-9 has predictive potential as a useful biomarker of stroke recovery in the field of cognition." (PMID 37371326, 2023). "It has been shown that in post-stroke patients the concentration of MMP9 is significantly higher compared to healthy volunteers." (PMID 37371326, 2023). "Western blotting revealed decreased levels of active MMP-9 in the CXI of μKO mice compared to WT 48 h after stroke." (PMID 37777791, 2023). "The level of MMP-9 is significantly increased after stroke onset, and the level is correlated with infarct size, stroke severity, and functional outcome." (PMID 37483355, 2023). "MMP-9 associated with D-dimer, BNP and S100b showed good sensitivity in the diagnosis of stroke and the differentiation between the various forms of stroke." (PMID 37511304, 2023). "Our new findings in this study demonstrate that stroke-induced activation of the SPAK–NKCC1 complex at the ChP is associated with barrier dysfunction, immune cell infiltration, activation of NF-κB and MMP9 signaling at the ChP." (PMID 35413993, 2022). "In physiological conditions, Mmp9 is expressed at low levels in the brain and is induced by neuronal activity, particularly strongly in pathological conditions such as epilepsy, stroke, TBA." (PMID 35992198, 2022). "Together, these findings reveal that dBET1 profoundly preserves the BBB integrity and protects against MMP-9 activation and neutrophil infiltration after stroke." (PMID 35761277, 2022). "In a rat ischemic stroke model, LTX4 was observed to ameliorate the course of stroke by inhibiting the matrix metallopeptidase 9 (MMP-9) pathway, dependent on nuclear factor kappa B (NF-κB) and regulating oxidative stress." (PMID 36672599, 2022). "Currently, EMMPRIN is considered to be a likely major regulator of BBB integrity after stroke, contributing to MMP-9 mediated BBB breakdown and recruitment of peripheral leukocytes into the CNS." (PMID 36119117, 2022). "Activated MMP-9 following stroke is known to degrade tight junction proteins and contribute to BBB disruption." (PMID 35761277, 2022). "Clinically, MMP-9 positively correlates with infarct volume and stroke severity, as well as worse neurological outcomes post-stroke." (PMID 36446955, 2022).